TLR4 (toll like receptor 4)
Diseases named in the same sentence as TLR4 in open-access papers (continued):
Sharing a sentence is not in itself a finding about the gene and the disease.
cancer (continued). "This evidence demonstrates that TLR4 activation of myeloid cells produces functional lymphatic progenitors and highlights the role of these progenitors in pathological conditions such cancer." (PMID 28598999, 2017). "LPS-triggered TLR4 signaling enhances cancer cell proliferation and leads to drug resistance in hepatoblastoma cells." (PMID 28881826, 2017). "Results showed that TLR4 expression level in cancer tissue was significantly higher than that in para-cancer tissue." (PMID 28484456, 2017). "Activation of the TLR4 signaling pathway results in cancer cell proliferation and angiogenesis in pancreatic cancer." (PMID 28881826, 2017). "In colorectal cancer (CRC), increased TLR4 levels are correlated with cancer stage, histological grade, metastasis, progression, and prognosis of CRC patients." (PMID 28881826, 2017). "Extract of larix leptolepis (ELL), which potentially activates TLR2 and TLR4 signaling, activates bone marrow-derived dendritic cells (BMDCs) to induce tumor-specific cytotoxic T lymphocytes (CTLs) against cancer." (PMID 28216575, 2017). "This is of particular relevance with regard to cancer treatment strategies, as the immunosuppressant drug Rapamycin decreases TLR4 expression and its prostaglandin E2 production." (PMID 29354132, 2017). "TLR4 is often overexpressed in malignant and tumor-infiltrating immune cells, and the application of TLR4 ligands in cancer therapies is desirable for enhancement of antitumor immunity." (PMID 28316978, 2017). "On the base of our former discovery, we also further explored the relationship between serum sTLR4 level and cancer tissue expressed TLR4 level." (PMID 28484456, 2017). "TLR4 induces inflammatory gene expression and contributes to the formation of inflammatory microenvironments, which promotes cancer development and metastasis." (PMID 29228698, 2017). "Positive TLR4 immunostaining was mainly observed in the cytomembrane and cytoplasm of carcinoma cells." (PMID 28484456, 2017). "TLR4 upregulate the NF-κB signaling and produce anti-apoptotic proteins that promote carcinogenesis and cancer cell growth and proliferation." (PMID 26675260, 2016). "The activation of ERK, JNK and p38 MAP kinases downstream of TLR4 has been proposed to be involved in the initiation and progression of cancer." (PMID 27323819, 2016). "TLR4 Activation by ligands leads to cytokine production that promotes a major role in the pathogenesis of same cancer, especially in initiation and maintenance of inflammation." (PMID 26771524, 2016). "TLR4 is the first human Toll homologue to be identified and has been demonstrated to be expressed not only on immune cells but also on various cancer cells." (PMID 27223258, 2016). "Recently, it has been shown that TLR2 and TLR4 antagonism produces an analgesic effect in behavioral tests in cancer pain models." (PMID 26962463, 2016). "The TLR4 or RAGE interaction with HMGB1 released from cancer cells engages downstream the PI3K and MAPK pathways to signal the myofibroblasts to proliferate, migrate and invade." (PMID 26979829, 2016). "It has been proposed that activation of TLR4 on immune cell is protective, while activation of cancer cell TLR4 promotes aggressiveness." (PMID 27909407, 2016). "Characterization of EOC cells that express TLR4/MD-2 and MyD88 have helped to confirm the dynamic role of the immunosuppressive microenvironment in promoting cancer metastasis and recurrence." (PMID 27118139, 2016). "Among several TLR subtypes, TLR4 is required for LPS stimulation and is involved in host defense against inflammation, apoptosis, and cancer." (PMID 27563334, 2016). "We further investigated the methylation status of putative Sp1 binding sites (CCCGCC), including a CpG site on the TLR4 promoter using quantitative methylation-specific PCR (qMSP) in gastric normal and cancer tissues." (PMID 26675260, 2016).
cancer (continued). "CCL-34, a synthetic bioactive glycolipid developed previously from our research team, has been reported as a TLR4 activator, promoting macrophage activation and macrophage-mediated cytotoxicity of cancer cells." (PMID 26883191, 2016). "Recently, cancers have been reported to become more invasive and aggressive following exposure to LPS via TLR4-MyD88 signaling pathway." (PMID 25691060, 2015). "For example, LPS has been shown to increase invasiveness in various cancer cells, and silencing TLR4 reduced their metastatic potential." (PMID 25691060, 2015). "Further evidence for the role of TLR4 as a resistin receptor came through the discovery that resistin-induced expression of SDF1 was mediated through interaction of resistin with TLR4 on stromal cancer cells." (PMID 26097512, 2015). "The present study revealed that the proliferation and survival of the cancer cells is regulated by a specific defense mechanism in TLR4/MyD88 signaling." (PMID 24527095, 2014). "Inflammation has been found to be intensified along with the increase in epidermal tumor malignancy, and the TLR4 signaling pathway has been considered to be a significant mediator of inflammation in a number of malignant tumors." (PMID 25118798, 2014). "Such DAMPs bind to receptors expressed on the surface of APCs (including TLR4), and not only boost their ability to engulf particulate material (including TAAs and cancer cell debris) but also trigger their maturation/activation." (PMID 25537519, 2014). "It has been reported for some cancers that TLR4 agonists represent promising vaccine adjuvants on the one hand and are successfully and safely used in classical monotherapy on the other hand." (PMID 25347345, 2014). "At the same time, published data suggest that TLR4 is required for protective immune response and killing of cancer cells." (PMID 25120541, 2014). "TLR4 can upregulate the NF-κB signaling and produce anti-apoptotic proteins that promote carcinogenesis and cancer cell growth and proliferation." (PMID 25179302, 2014). "When the function of TLR4 signaling pathways is gradually unveiled and confirmed in cancer cells, their regulation attracts much attention." (PMID 25179302, 2014). "The effects of TLR signaling in cancer cells have been extensively investigated for TLR4, perhaps the best-studied PRR." (PMID 25101083, 2014). "It is possible that TLR4 exerts pro- or anti-cancer effects, depending on the prevailing conditions in the tissue microenvironment during different phases of cancer development or metastasis." (PMID 25120541, 2014). "On the other hand, TLR2 and TLR4 protein levels shown were focused on normal and cancerous tissues in relation to healthy patients and cancer patients." (PMID 25547486, 2014). "In summary, cancer-derived IgG promotes LPS-induced proinflammatory cytokine production via interacting with TLR4 and enhancing its expression." (PMID 25179302, 2014). "TLR4 agonists have immune regulatory applications as adjuvants in vaccines and in the treatment of chronic viral infection and cancer therapy." (PMID 25076949, 2014). "This review article provides a brief summary of the current understanding of TLR4-signaling, its pro- and anti-cancer effects, and the therapeutic potential of TLR4 immunomodulation in the prevention and treatment of cancer." (PMID 25120541, 2014). "Experimental evidence suggests that cancer cell migration and invasion are induced by triggering of TLR4-NF-κB under inflammatory conditions." (PMID 25120541, 2014). "Adjuvant studies for cancer vaccine treatments have recently focused on TLR4 agonists because these receptors mediate signals from the innate immune system via MyD88- and TRIF-dependent pathways, and these appear to be important immunopotentiators." (PMID 25102137, 2014).
cancer (continued). "Although mechanism is not fully understood, TLR4 can induce an efficient cancer antigen-specific cytotoxic T cell immune response." (PMID 25120541, 2014). "In these scenarios of established cancer, TLR4 facilitates an environment that is suitable for continued cancer cell proliferation." (PMID 25120541, 2014). "Derived from LPS as a potent TLR4 agonist, MPL is an active component of Cervarix, which is used against cancer-causing human papillomavirus (HPV)." (PMID 25101092, 2014). "In parallel, expression of TLR4 and MyD88 mRNA and regulatory microRNAs (miR-21 and miR-146a) was assessed, as well as in a series of chemosensitive and resistant cancer cells lines." (PMID 24977712, 2014). "LPS-induced TLR4-signaling also promotes cancer cell survival and proliferation in hepatocellular carcinoma." (PMID 25120541, 2014). "This cancer vaccine consists of recombinant MAGE-A3 protein formulated in saponin-containing QS-21 liposomes containing the TLR-4 and TLR-9 agonists, MPL and CpG oligodeoxynucleotides." (PMID 26344626, 2014). "Our animal data combined with the human data presented in the current manuscript argue for studying TLR4 antagonists in cancer." (PMID 24887394, 2014). "Clinical and experimental studies indicate that TLR4 plays a significant role in connecting inflammation and cancer invasion and progression, but the exact mechanism is still not clear." (PMID 24363762, 2013). "It has been recognized that HMGB1 plays an important role in autoimmunity disease and cancers, and HMGB1, TLR4 and NF-κB have all been shown to participate in the progression and metastasis of malignant tumors." (PMID 23803172, 2013). "Our studies showed that the majority of dysplasia and cancers occurring in the setting of IBD demonstrate over-expression of toll-like receptor 4 (TLR4)–the receptor for lipopolysaccharide (LPS) from Gram-negative bacteria." (PMID 23691015, 2013). "Tumors arising in villin-TLR4 mice are characterized by intense nuclear β-catenin staining and a population of Lgr5-positive cells, a marker of cancer stem cells." (PMID 23691015, 2013). "The differences in expression of the two molecules between carcinoma tissues and normal thyroid tissues were all found to be statistically significant (TLR4, P < 0.001; CXCR7, P < 0.001)." (PMID 24363762, 2013). "In agreement with other reports, we demonstrated very low constitutive expression of both TLR2 and TLR4 on the surface of neutrophils isolated from the blood of cancer patients, as well as of the control group." (PMID 22528050, 2012). "To date, very few endogenous ligand(s) that initiate the TLR4 signaling pathway in the CNS post-nerve injury or cancer development have been identified." (PMID 22607655, 2012). "In general, TLR4 was found to be expressed in normal ovarian epithelium, benign cysts, borderline tumors and malignant tumors." (PMID 22533866, 2012). "The expression of TLR2 and TLR4 on the surface of freshly isolated as well as PMA- or fMLP-stimulated neutrophils of cancer patients versus healthy individuals (control group) was assessed using FCM." (PMID 22528050, 2012). "There were no statistical differences between the expression of TLR2 and TLR4 on unstimulated neutrophils of cancer patients and healthy donors." (PMID 22528050, 2012). "TLR4 has been detected in many human cancer cell lines, including pancreatic, lung, breast, prostate, liver and colorectal cancer." (PMID 22938142, 2012). "In this study, upregulation of TLR4 mRNA in bilateral spinal dorsal horn at 8 and 16 days after cancer cell-inoculation was observed." (PMID 22607655, 2012). "All these results provide a possibility that TLR4- NF-κB pathway is a connection between inflammation, immunity and cancer." (PMID 22195048, 2011). "No prior study has shown an effect of HMGB1 on MMP-2 and TIMP-3 whereas it has been recently reported that HMGB1 enhances MMP-9 expression in neurons, via Toll-Like Receptor 4 signaling, and in cancer cells via NF-κB signalling." (PMID 21731608, 2011).
cancer (continued). "Nevertheless, TLR4 engagement by endotoxin as well as by endogenous ligands represents notable contribution to the outcome of different cancer treatments, such as radiation or chemotherapy." (PMID 22110526, 2011). "Perturbation of the STAT1/3 balance induced by the different timing regimens of TLR4/9 agonist complex application directed cytokine/growth factor signals from apoptotic to proliferative or from cancer immunosurveillance to cancer immunoediting." (PMID 21931823, 2011). "Elucidating how TLR4-mediated regulation of epithelial proliferation leads to cancer will provide a novel insight into the pathogenesis of inflammation-induced tumorigenesis in the intestine." (PMID 24212947, 2011). "Human beast cancer cell line MDA-MB-231 showed that siRNA-directed knockdown of the TLR4 gene was specific." (PMID 20618976, 2010). "The GSEA revealed that cancer-related gene modules were remarkably enriched in patients with upregulated TLR4, TLR2, TLR1 and PYCR1 (TLR4upTLR2upTLR1upPYCR1up) compared with patients with a downregulated expression of these markers (TLR4downTLR2downTLR1downPYCR1down)." (PMID 41254241, 2025). "BGN has been reported to bind both TLR2 and TLR4 in various cell types, including cancer cells." (PMID 41465449, 2025). "The TLR-4 expression in TLR4 + cancer cells was significantly up-regulated after PTX treatment, while there was no significant change in TLR4 − cancer cells after treatment, and the TLR-4 expression level in BC cells was positively correlated with the survival rate after PTX treatment." (PMID 40404908, 2025). "These compounds are used to target different nuclear receptors of cancer which includes peroxisome proliferator-activated receptor gamma (PPARγ), toll-like receptor 4 (TLR4), brain-derived neurotrophic factor (BDNF), and peroxisome proliferator-activated receptor alpha (PPARα)." (PMID 41459064, 2025). "The difficulty in determining whether TLR4 should be inhibited or stimulated during cancer treatment is further exacerbated by the different effects of TLR4 on the immune system." (PMID 40878805, 2025). "Indeed, human umbilical endothelial cells or cancer cells showed reduced Stx binding upon small interfering RNA-mediated TLR4 depletion." (PMID 40740497, 2025). "Furthermore, paeonol inhibits cancer cell growth, proliferation, invasion and metastasis by inducing cell apoptosis and the suppression of the TLR4/NF-κB/STAT3/MAPK/PI3K/AKT/CHOP/VEGF/HIF-1α, pathways." (PMID 40083771, 2025). "On the one hand, in cancer patients, TLR4 (expressed by immunocytes) can mediate activation of innate or adaptive immunity, and could confer benefit, as several reports indicate the potency of TLR agonists in enhancing antitumor immune responses." (PMID 40868123, 2025). "For extrahepatic tumors, circulating LPS may directly activate TLR4-expressing cancer cells or stromal components." (PMID 40444051, 2025). "Importantly, several key ferroptosis drivers and suppressors, including MAPK1, TLR4, ATM, ULK2, NFS1, and HMOX1, have been identified, offering potential therapeutic targets to modulate cancer cell susceptibility to ferroptosis." (PMID 40868287, 2025). "Several studies have proposed a role for TLR4 in cancer progression and resistance." (PMID 40878805, 2025). "Although we did not directly investigate the anticancer properties of T19093 in this study, its inhibitory effects on TLR4/MD2 may suggest potential immunomodulatory benefits in cancer therapy." (PMID 39976020, 2025). "Alterations in gut microbiota in cancer cachexia substantially enhance the presence of Gram-negative bacteria, which, in turn, trigger pro-inflammatory responses by binding lipopolysaccharides (LPS) to toll-like receptor 4 (TLR4)." (PMID 40129936, 2025). "TLR4 on the surface of immune and cancer cells recognizes LPS." (PMID 40666174, 2025). "This evidence suggests that inhibiting TLR4 could be an effective treatment strategy against cancer." (PMID 40878805, 2025).
cancer (continued). "On the other hand, it was suggested that endotoxin-triggered activation of TLR4 found on carcinoma cells may contribute to cancer progression/resistance to therapy in tumors of various anatomic sites." (PMID 40868123, 2025). "Using in vitro co‐culture experiments and in vivo mouse models, we demonstrated that chronic stress‐regulated and β‐adrenergic stimulation‐induced TDEs remodeled neutrophils via the TLR4‐NFκβ pathway, which established exosomes as important mediators of immune regulation in the context of cancer." (PMID 39630109, 2025). "Moreover, the effect of AMK on signaling pathways such as Wnt/β-catenin, TLR4/MyD88, and mitochondrial pathways suppress cancer cell proliferation, increase cancer cell apoptosis, and improve responses to chemotherapy agents." (PMID 40144663, 2025). "The expression profile of TRPV1 and innate immunity toll-like receptor 4 (TLR4) was also assessed in the L3–5 DRG sensory neurons, corroborating the association between these two receptors based on their co-expression on DRG cells of the cancer-induced model." (PMID 38730655, 2024). "Research indicates that visfatin may bind to C-C chemokine receptor 5 (CCR5) in cancer cells as an antagonist and promote inflammation by enhancing Toll-like receptor 4 (TLR4)-mediated pathways." (PMID 38929716, 2024). "Activation of the TLR4/NF-κB pathway leads to increased production of cytokines, growth factors, and proteases that promote angiogenesis and resistance to apoptosis, allowing cancer cells to survive and grow." (PMID 39451226, 2024). "Additionally, caspase‐4/5/11 activators like TAK‐242, a TLR4 inhibitor studied for sepsis, have shown effectiveness in reducing inflammatory responses and are being considered for repurposing in cancer therapy." (PMID 39239068, 2024). "Furthermore, TLR4 signaling induces properties akin to cancer stem cells and facilitates epithelial-mesenchymal transition (EMT), a process implicated in cancer metastasis." (PMID 38903515, 2024). "Therefore, both heparan sulfate and TLR4 activation favor cancer stem-like properties, but active heparanase is essential for the whole process." (PMID 39349458, 2024). "Previous research has linked TLR4 and TLR9 activation to cancer growth in a variety of situations." (PMID 38476365, 2024). "Targeting TLR4, especially in combination with traditional drug treatments, could represent a novel strategy for more effectively eliminating cancer cells." (PMID 38254888, 2024). "TLR4 is expressed both on immune cells and cancer cells and thus acts as a double-edged sword." (PMID 39684439, 2024). "Moreover, TLR4 activation is related to the immune escape of cancer cells, inducing the resistance of cancer cells against cytotoxic T lymphocytes, and the activation of TLR4/Akt signaling promotes the development of cancer." (PMID 39075517, 2024). "The stimulation of TLR4/MD2 complex signaling by LPS may involve loss or mutation of the tumor suppressor PTEN36, which can have a significant impact on cancer susceptibility and tumorigenesis, even with subtle changes in its function." (PMID 38472293, 2024). "Considering the pivotal roles of both integrin β6 and TLR4 in tumorigenesis, these findings suggest that bacterial infections may serve as triggers for cancer development in the HPV-infected cervical epithelium." (PMID 38254888, 2024). "TLR-4 activation in cancer cells may promote upregulation of anti-apoptotic proteins and DNA repair mechanisms, reducing sensitivity to cisplatin-induced cell death." (PMID 39124797, 2024). "LPS serves as the primary activator of TLR4 across various cancer types, including NSCLC and CRC." (PMID 38612546, 2024). "Further mechanistic insights have been gained from examining skeletal muscle atrophy in cancer cachexia, where it has been reported that cancer cells activate Toll-like receptor 4 in skeletal muscle, which then phosphorylates CBP/p300 via the p38β–MAPK pathway." (PMID 38978023, 2024).